RNU6-1031P (RNA, U6 small nuclear 1031, pseudogene)
Gene: Small nuclear RNA gene on chromosome 1 (67,541,127 to 67,541,233, forward strand). Ensembl gene ENSG00000207504.
Homologues: Orthologues: chimpanzee U6 (97% identical), macaque U6 (94% identical), dog U6 (81% identical). Paralogues in human: RNU6-1316P (92% identical), RNU6-20P (92% identical), RNU6-35P (92% identical), RNU6-39P (92% identical), RNU6-434P (92% identical), RNU6-1145P (91% identical), RNU6-16P (91% identical), RNU6-25P (91% identical), RNU6-29P (91% identical), RNU6-38P (91% identical), RNU6-393P (91% identical), RNU6-46P (91% identical), and 1286 more.